AKT3 (AKT serine/threonine kinase 3)
Diseases named in the same sentence as AKT3 in open-access papers (continued):
Sharing a sentence is not in itself a finding about the gene and the disease.
Focal cortical dysplasia (5 papers, 2015 to 2022). A type of malformation of cortical development that primarily affects areas of neocortex. "Focal cortical dysplasias (FCDs) are localized MCDs, formerly believed to mostly result from a toxic insult to the developing brain, but recently also associated with DEPDC5 mutations and somatic mutations in MTOR, PIK3CA, AKT3, PTEN, TSC1 and TSC2." (PMID 35323703, 2022).
malignant glioma (5 papers, 2015 to 2024). A grade III or grade IV glioma arising from the central nervous system. "The low mRNA level of AKT3 was associated with a higher grade of malignant glioma." (PMID 25997610, 2015). "Furthermore, AKT3 is known to play an active role in the survival of human malignant glioma cells." (PMID 37761812, 2023).
osteoarthritis (5 papers, 2019 to 2023). A noninflammatory degenerative joint disease occurring chiefly in older persons, characterized by degeneration of the articular cartilage, hypertrophy of bone at the margins and changes in the synovial membrane. "Recently, PVT1 regulated miR-497/AKT3 pathway and influenced the function of osteoarthritis cells via regulation of proliferation, apoptosis and ECM degradation in chondrocytes." (PMID 37779916, 2023). "For example, in osteoarthritis, MALAT1 promotes inflammatory progression and extracellular matrix degradation by regulating the miR-150-5p/AKT3 axis." (PMID 38114929, 2023).
polymicrogyria (5 papers, 2017 to 2025). A developmental brain abnormality characterized by an excessive amount of small convolutions on the surface of the brain and cognitive dysfunction. "Regarding head MRI findings, enlargement of the ventricle, polymicrogyria, and white matter abnormalities were observed in all patients with AKT3 or PIK3R2 mutations, and seemed indicative of mTOR pathway involvement." (PMID 28086757, 2017). "The patient carrying a large (>100 Mb) duplication involving, among many other genes, HNRNPU and AKT3, had a complex phenotype including neonatal seizure onset, polymicrogyria, and multiple cardiac defects." (PMID 30866059, 2019). "Mutations in Akt3 have been implicated in Megalencephaly-Polymicrogyria-Polydactyly-Hydrocephalus Syndrome (MPPH syndrome) where all individuals have a cortical brain malformation called polymicrogyria." (PMID 40048438, 2025). "However, individuals with polymicrogyria and documented macrocephaly had variants only in genes encoding components of or related to the mTOR pathway (PIK3R2, PI3KCA, AKT3, and PTEN)." (PMID 37486637, 2023). "Regarding brain MRI findings, while ventriculomegaly, polymicrogyria and white matter abnormalities were observed in all patients with AKT3 and PIK3R2 mutations, no obvious abnormalities were found in patients with PTEN mutations." (PMID 28086757, 2017).
brain tumors (4 papers, 2011 to 2024). "During this procedure, SNUH utilized NGS with a brain tumour-targeted gene panel, identifying the TPM3::NTRK1 fusion, amplification of MDM4/AKT3, and one-copy loss of PTEN/FGFR2, leading to the diagnosis of the tumour as HGG, not otherwise specified (NOS), according to the WHO2021 criteria." (PMID 39014476, 2024).
breast tumor (4 papers, 2011 to 2022). "In addition, basal breast tumors are characterized by low ER and PR expression as well as high levels of EGFR, elevated expression of AKT3, CD44 and MET and decreased GATA3 expression; features that are also consistent with each of the HER2 related subgroups investigated in the current study." (PMID 21672245, 2011).
cutaneous melanoma (4 papers, 2012 to 2022). A primary melanoma arising from atypical melanocytes in the skin. "Moreover, TCGA cutaneous melanoma project has revealed low-frequency pathogenetic mutations in AKT3 (0.3%) and FGF3 (2.5%)." (PMID 33317587, 2020). "Nanoliposomal-mediated siRNA targeting of (V600E)B-Raf and Akt3 led to a cooperatively acting approximately 65% decrease in early or invasive cutaneous melanoma compared with inhibition of each singly with negligible associated systemic toxicity." (PMID 22623890, 2012). "Thus, cationic nanoliposomes loaded with siRNA targeting (V600E)B-Raf and Akt3 provide an effective approach for targeted inhibition of early or invasive cutaneous melanomas." (PMID 22623890, 2012).
Intellectual disability (4 papers, 2015 to 2022). "AKT3 shows prenatal enrichment during human neocortical development and recurrent copy number variations involving the 1q43-44 locus are associated with cortical malformations and intellectual disability, implicating an essential role in early brain development." (PMID 28467426, 2017). "AKT3 genetic abnormalities result in intellectual disabilities, and deficits in temporal order discrimination and spatial memory are seen in AKT3 knockout mice." (PMID 36386965, 2022). "This has also been proposed in a study in which two patients with moderate-to-severe intellectual disability, craniofacial anomalies, and seizures carrying 1q44 microdeletion including both ZNF238 and AKT3 both had MIC, but only the one presented with CCA." (PMID 25722899, 2015).
Macrocephaly (4 papers, 2019 to 2025). Occipitofrontal (head) circumference greater than 97th centile compared to appropriate, age matched, sex-matched normal standards. "The association of AKT3 copy number gains with the mirror phenotype (macrocephaly) has also been reported in literature." (PMID 30853971, 2019). "Megacephaly polymicrogyria, polydactyly, hydrocephalus (MPPH) is an extremely rare condition caused by a defect in the AKT3, CCND2, or PIKR2 genes." (PMID 34354878, 2021).
meningioma (4 papers, 2012 to 2023). A generally slow growing tumor attached to the dura mater. "We observed that both PI3K (PIK3R1, PIK3R3) and Akt (AKT3) genes were up-regulated in fibroblastic meningioma, and total Akt and phosphorylation Akt were also overexpressed in tumor tissues." (PMID 23285163, 2012).
Stroke (4 papers, 2020 to 2026). Sudden impairment of blood flow to a part of the brain due to occlusion or rupture of an artery to the brain. "Moreover, previous studies demonstrated that Akt3 was expressed at low levels in the ischemic brain after stroke, and constitutive activation of Akt3 inhibited neuronal death induced by oxygen–glucose deprivation in vitro and reduced brain infarction size in a rat stroke model." (PMID 36062010, 2022).
viral infection (4 papers, 2017 to 2022). "PARP9 mediates the production of type I interferon after binding to viral RNA by activating the PI3K/AKT3 signaling pathway, thereby protecting against viral infection." (PMID 36212830, 2022). "Moreover, it is possible to enhance anti-viral immunity by promoting serine/threonine kinase 3 (AKT3) activation; a positive feedback loop is formed via type I IFN signaling and 7DHC accumulation to amplify innate immune responses and control viral infection by activating AKT3." (PMID 35529872, 2022). "At day 3 of viral infection, we found that blocking Akt3, but not Akt1, Akt2, or Akt1 plus 2, resulted in an inhibition of colony growth and obvious floating, dead cells." (PMID 28483982, 2017).
acute myeloid leukemia (3 papers, 2016 to 2022). Acute myeloid leukemia (AML) is a group of neoplasms arising from precursor cells committed to the myeloid cell-line differentiation. "The first two pathways that are worth mentioning are associated (i) with the ErbB receptor signaling and (ii) with genes (c-KIT, STAT3, AKT3) that have been mainly described as increased in acute myeloid leukemia, in which the crucial role of CEBPA has been widely demonstrated." (PMID 26496024, 2016).
astrocytoma (3 papers, 2019 to 2022). "Overexpression of AKT3-174aa inhibited cell proliferation, radiation resistance, and in vivo tumorigenicity in GBM cells, whereas circ-AKT3 knockdown improved the malignant characteristics of astrocytoma cells." (PMID 35883576, 2022). "AKT3-174aa overexpression decreased the cell proliferation, radiation resistance and in vivo tumorigenicity of GBM cells, while the knockdown of circ-AKT3 enhanced the malignant phenotypes of astrocytoma cells." (PMID 31470874, 2019). "Based on the ranking results, four genes (RAF1, AKT3, IDH1, and FGFR1) were independent predictors of the survival status of astrocytoma patients." (PMID 31620163, 2019). "We detected that 18 genes were respectively correlated with overall survival in astrocytoma; moreover, four genes (RAF1, AKT3, IDH1, and FGFR1) were detected as dependent variables for the prediction of the survival status of astrocytoma patients and were capable to predict the survival." (PMID 31620163, 2019).
esophageal squamous cell carcinoma (3 papers, 2021 to 2024). Esophageal squamous cell carcinoma (ESCC) is a type of esophageal carcinoma (EC) that can affect any part of the esophagus, but is usually located in the upper or middle third. "miR-3680-3p was shown to be sponged by circ-PRKCI to regulate AKT3 expression in esophageal squamous cell carcinoma." (PMID 36941990, 2023). "Meanwhile, it has been found that circPRKCI is a ceRNA to enhance AKT3 expression in esophageal squamous cell carcinoma via sponging miR-3680-3p." (PMID 34695805, 2021).
mastitis (3 papers, 2018 to 2021). Inflammation of breast tissue during lactation or postpartum due to an obstructed duct or infection. "The association and gene expression for AKT3 with mastitis and its role in immune response as well as the sequence differences between cow and buffalo has not been reported yet." (PMID 34677734, 2021). "The identification of sequences differences of AKT3 and core promoter confirmation play an important key role in gene expression in cow and buffalo milk production and immune response against mastitis." (PMID 34677734, 2021). "This study emphasized the great importance of the structural differences of AKT3 between the animal species on their different responses against immune diseases like mastitis." (PMID 34677734, 2021). "And, evaluation of AKT3 inflammatory response to the lipopolysaccharide (LPS)-induced mastitis was performed between both species." (PMID 34677734, 2021). "Therefore, the mastitis model based on the relationship between LPS and AKT3 can provide a good platform for dairy cow mastitis research." (PMID 34677734, 2021). "For the immune response of AKT3 and LPS, the conjugation between LPS and AKT3 which is related to the immune response is important for predicting mastitis in its early stage of Gram-negative infections." (PMID 34677734, 2021).
MPPH syndrome (3 papers, 2020 to 2025). "Since both WDR62 and Akt3 mutations impinge upon Aurora B, Aurora B dysfunction may be a key regulator of MPPH syndrome." (PMID 40048438, 2025). "Megalencephaly-polymicrogyria-polydactyly-hydrocephalus (MPPH) syndrome is caused by mutations, in order of frequency, of either PIK3R2, AKT3, or CCND2 genes with consequent activation of the PI3K-AKT-mTOR pathway." (PMID 35096710, 2021).
myocardial infarction (3 papers, 2023 to 2025). Gross necrosis of the myocardium, as a result of interruption of the blood supply to the area, as in coronary thrombosis. "In adult hearts, Akt3 has been implicated as a key mediator of the anti-apoptotic effects of miRNA-145 during myocardial infarction." (PMID 40048438, 2025). "For instance, the Akt3/mTOR signaling pathway regulates apoptosis induced by myocardial infarction via autophagy, indicating that Akt3 could regulate autophagy." (PMID 37511199, 2023).
neuroblastoma (3 papers, 2013 to 2017). Neuroblastoma (NB) is the most common solid, extracranial childhood tumor. "The differential expression of AKT3, GNAI2, and IL21 was analyzed by comparing expression levels in murine neuroblastoma cells infected by the wild type RABV with control uninfected cells using RT-qPCR." (PMID 27872612, 2016). "In this study, we found that silencing AKT2, but not AKT1 or AKT3 suppresses N-myc expression in neuroblastoma cells." (PMID 23468863, 2013). "miR-122 was reported to play a pivotal role as tumor suppressor by decreasing AKT3 levels, inhibiting cell migration and proliferation and inducing apoptosis, whereas miR-184 was found to be involved in suppressing cell survival and growth by targeting AKT2 in neuroblastoma cells." (PMID 28052756, 2017). "Since, GRP-R silencing specifically inhibited the expression of AKT2 isoform, but not AKT1 or AKT3, we can further conclude that GRP-R-mediated regulation of N-myc expression in neuroblastoma cells is AKT2-dependent." (PMID 23468863, 2013). "Moreover, GRP-R modulates N-myc expression in neuroblastoma cells by AKT2 isoform, but not the AKT1 or AKT3." (PMID 23468863, 2013). "Interestingly, silencing GRP-R predominantly reduces AKT2 expression without affecting the expression of AKT1 or AKT3 isoform, thus demonstrating a more critical role of AKT2 in GRP-R-mediated neuroblastoma tumorigenesis." (PMID 23468863, 2013).
oral cancer (3 papers, 2019 to 2020). "Our preliminary study indicated that Akt1 and 2 are primarily overexpressed in oral cancer tissues and also the TCGA dataset revealed the genetic alteration associated with Akt1 and 2 isoforms increased the transcript level but not the Akt3 isoform." (PMID 31252679, 2019). "ME decreased the phosphorylation of Akt by ~ 50% in oral cancer cells (data not shown), and based on the RNA-seq, the expression of Akt3 was markedly suppressed in tumors from ME-treated mice." (PMID 32264893, 2020). "The immunohistochemical analysis of oral cancer tissues showed an overexpression of Akt1 and 2 isoforms but not Akt3." (PMID 31252679, 2019). "On exploring the TCGA dataset, it was observed that all three Akt kinase isoforms have a considerable percentage of genetic alterations in HNSCC, but in our study, the IHC analysis of oral cancer tissues showed high expression of Akt1 and 2 isoforms but not Akt3 compared to the normal tissues." (PMID 31252679, 2019). "However, the major limitation of our study is the lack of detailed mechanistic involvement of the Akt3 isoform in oral cancer, which can be evaluated in the near future to get an in-depth understanding of the disease." (PMID 31252679, 2019).
Parkinson disease (3 papers, 2021 to 2024). A progressive degenerative disorder of the central nervous system characterized by loss of dopamine producing neurons in the substantia nigra and the presence of Lewy bodies in the substantia nigra and locus coeruleus. "One study examined how inhibiting miR-15b-5p will suppress cell death in Parkinson’s disease (PD) by focusing on the Akt3-mediated GSK-3/catenin signaling pathway." (PMID 36187290, 2022).
prostate tumors (3 papers, 2015 to 2021). "Immunohistochemical staining of 65 clinical samples revealed that AKT3 protein expression was higher in prostate tumors of stage I, II, III as compared to nearby normal tissues." (PMID 26318033, 2015). "We further determined the protein level of AKT3 in normal and cancer prostate tissues by immunohistochemical staining (IHC) in 38 normal prostate epithelial tissues and 27 primary prostate tumors including stage I, II, and III." (PMID 26318033, 2015). "We demonstrated that AKT3 mRNA and protein expression was elevated in primary prostate tumors as compared to normal prostate tissues." (PMID 26318033, 2015). "Our observation suggested that AKT3 mRNA is higher in prostate tumors as compared to normal prostate tissues, suggesting that upregulation of transcription can at least partially contribute to the increase of AKT3 protein expression." (PMID 26318033, 2015). "The qRT-PCR analysis of 139 clinical samples and analysis of 150 on-line database clinical samples indicated that AKT3 mRNA expression level was elevated in primary prostate tumors." (PMID 26318033, 2015). "We believe that treatment with AKT3 inhibitor, such as Isoselenocyanates, may suppress the growth of primary prostate tumors." (PMID 26318033, 2015). "AKT3 protein expression was higher in primary prostate tumors as compared to normal tissue." (PMID 26318033, 2015). "However, we don't know whether elevation of AKT3 in prostate tumors directly contributes to the increase of phosphorylation of AKT in prostate tumors or not." (PMID 26318033, 2015). "However, we believe that the elevation of AKT3 protein at least partially increases the phosphorylation of AKT on Ser473 and Thr308 in prostate tumors." (PMID 26318033, 2015). "The IHC staining indicated that AKT3 protein level is approximately two fold higher in primary prostate tumors as compared to nearby non-malignant prostate tissues." (PMID 26318033, 2015). "However, low or negative Akt3 protein expression has been found in the majority of malignant prostate tumor samples examined (The Human Protein Atlas)." (PMID 34591413, 2021).
stomach cancer (3 papers, 2021 to 2022). "Together, the identification of these ECM pathways and the co-expression of AKT3 and DDR2 in E-cadherin-low gastric tumours suggest an active link between ECM remodelling and AKT3 signalling in DGC." (PMID 35406381, 2022). "Since there are no isoform-specific small molecule inhibitors of AKT3, we sought to identify an indirect route to target this protein in E-cadherin-deficient cells by identifying AKT3-associated genes in CDH1-low gastric tumours." (PMID 35406381, 2022). "Gene expression analysis of gastric tumour samples from The Cancer Genome Atlas (TCGA) stomach adenocarcinoma (STAD) cohort revealed that the expression of the AKT3 isoform (but not AKT1 or AKT2) is inversely correlated to the expression of CDH1 in gastric tumours." (PMID 35406381, 2022).
adenoma (2 papers, 2021 to 2022). A neoplasm arising from the epithelium. "These genes were involved in different stages of cancer development as analyzed using the KEGG pathway, this includes SMAD4 and TGFBR1 at the late adenoma, and AKT3 and PIK3R2 at the carcinoma stage in CRC development." (PMID 36499586, 2022). "The results also included previously unreported genes including AKT3, NCOR2, PIK3R2, SMAD4, and TGFBR1, from which AKT3 and PIK3R2 were present in the early adenoma stage and SMAD4 and TGFBR1 were present at the late adenoma stage." (PMID 36499586, 2022).
Alzheimer disease (2 papers, 2021 to 2022). A progressive, neurodegenerative disease characterized by loss of function and death of nerve cells in several areas of the brain leading to loss of cognitive function such as memory and language. "Ten DEGs, including IGF1, VEGFC, RAPGEF3, PIK3CA, Akt3, ITGB3, ITGA11, SPP1, NOS1, and ATP6V0B, were selected from Rap1, oxidative phosphorylation, and Alzheimer’s disease signaling pathways." (PMID 34359260, 2021).
amyotrophic lateral sclerosis (2 papers, 2019 to 2021). Amyotrophic lateral sclerosis (ALS) is a neurodegenerative disease characterized by progressive muscular paralysis reflecting degeneration of motor neurons in the primary motor cortex, corticospinal tracts, brainstem and spinal cord. "Properly regulated AKT3 gene expression may be neuroprotective in other inflammatory neurological disorders, such as amyotrophic lateral sclerosis (ALS) and Parkinson’s disease (PD)." (PMID 33920138, 2021). "Akt3 is significantly upregulated during spinal cord injury in rats, is neuroprotective in a mouse model of Familial Amyotrophic Lateral Sclerosis (ALS) and EAE, and has been identified as the most prominent Akt isoform involved in the protection against neurodegeneration." (PMID 31404142, 2019).